DUSP21 (dual specificity phosphatase 21)
Description:
Protein phosphatase component of the sperm flagellar doublet microtubules (By similarity). May act as a regulator of sperm motility by mediating dephosphorylation of sperm doublet microtubule proteins (By similarity). Can dephosphorylate single and diphosphorylated synthetic MAPK peptides, with preference for the phosphotyrosine and diphosphorylated forms over phosphothreonine (By similarity).
Synonyms: LMWDSP21
Tractability: Antibody: UniProt places it where antibodies can reach, with medium confidence.
Gene: Protein-coding gene on chromosome X (44,844,021 to 44,844,888, forward strand). Ensembl gene ENSG00000189037.
Subcellular location: Cytoplasm; Nucleus; Mitochondrion inner membrane; Cytoplasm, cytoskeleton, flagellum axoneme
Subcellular location (Human Protein Atlas): Centrosome; Connecting piece; Mid piece; Nucleoli; Principal piece
Gene Ontology:
Molecular function: protein binding; protein tyrosine phosphatase activity; protein serine/threonine phosphatase activity; MAP kinase tyrosine/serine/threonine phosphatase activity; phosphoprotein phosphatase activity
Biological process: peptidyl-tyrosine dephosphorylation; flagellated sperm motility
Cellular component: cytoplasm; nucleolus; nucleus; axonemal A tubule inner sheath; mitochondrial inner membrane; sperm flagellum; mitochondrial matrix
Homologues: Orthologues: chimpanzee DUSP21 (98% identical), macaque DUSP21 (85% identical), dog DUSP21 (71% identical), rat Dusp21 (71% identical), mouse Dusp21 (69% identical), rabbit DUSP21 (68% identical), tropical clawed frog dusp18 (45% identical). Paralogues in human: DUSP18 (69% identical), DUSP14 (45% identical), SSH3 (29% identical), DUSP26 (28% identical), DUSP13B (28% identical), DUSP16 (28% identical), DUSP8 (28% identical), SSH2 (28% identical), STYXL2 (28% identical), DUSP1 (27% identical), SSH1 (27% identical), DUSP10 (27% identical), and 19 more.
Diseases named in the same sentence as DUSP21 in open-access papers:
DUSP21 is named in the same sentence as 5 diseases in open-access papers, as found by Europe PMC text mining. Sharing a sentence is not in itself a finding about the gene and the disease.
DUSP21 shares sentences with these, for which no sentence is quoted: cancer (2 papers); asthma (1); colorectal cancer (1); glioma (1); melanoma (1).